TRAPPC8 (trafficking protein particle complex subunit 8)
Description:
Plays a role in endoplasmic reticulum to Golgi apparatus trafficking at a very early stage. Maintains together with TBC1D14 the cycling pool of ATG9 required for initiation of autophagy. Involved in collagen secretion.
Synonyms: KIAA1012; HsT2706; TRS85; GSG1
Tractability: PROTAC: ubiquitination databases record sites on it; its protein half-life has been measured.
Gene: Protein-coding gene on chromosome 18 (31,829,197 to 31,953,136, reverse strand). Ensembl gene ENSG00000153339.
Subcellular location: Golgi apparatus, cis-Golgi network
Subcellular location (Human Protein Atlas): Cytosol; Microtubules
Pathways (Reactome):
Vesicle-mediated transport: RAB GEFs exchange GTP for GDP on RABs
Gene Ontology:
Molecular function: protein binding
Biological process: collagen biosynthetic process; Golgi organization; COPII vesicle coating; endoplasmic reticulum to Golgi vesicle-mediated transport
Cellular component: TRAPP complex; cytoplasm; cytosol; TRAPPIII protein complex; Golgi apparatus
Genetic constraint (gnomAD): Loss-of-function variants: 49 observed, 147.58 expected, observed/expected ratio (o/e) 0.33, 90% interval 0.26 to 0.42. The upper end of that interval is the gene's LOEUF score, 0.42, which puts it in group 1 of 6, group 1 being the genes least tolerant of losing a copy. Missense variants: 1,392 observed, 1,598.7 expected, observed/expected ratio (o/e) 0.87, 90% interval 0.83 to 0.91. Synonymous variants: 585 observed, 552.02 expected, observed/expected ratio (o/e) 1.06, 90% interval 0.99 to 1.13.
Homologues: Orthologues: chimpanzee TRAPPC8 (99% identical), macaque TRAPPC8 (99% identical), dog TRAPPC8 (96% identical), pig TRAPPC8 (96% identical), rabbit TRAPPC8 (95% identical), mouse Trappc8 (92% identical), rat Trappc8 (91% identical), guinea pig TRAPPC8 (87% identical), tropical clawed frog trappc8 (78% identical), zebrafish trappc8 (68% identical), Drosophila melanogaster l(3)76BDm (28% identical), Caenorhabditis elegans trpp-8 (20% identical).
Diseases named in the same sentence as TRAPPC8 in open-access papers:
TRAPPC8 is named in the same sentence as 5 diseases in open-access papers, as found by Europe PMC text mining. Sharing a sentence is not in itself a finding about the gene and the disease. The quoted sentences say what the papers report.
ciliopathy (1 paper, 2020). A genetic disorder of the cellular cilia or the cilia anchoring structures, the basal bodies, or of ciliary function. "We found a ciliopathy protein, oral-facial-digital syndrome 1 (OFD1), interacting with the TRAPPIII-specific subunits TRAPPC8 and TRAPPC12." (PMID 32258032, 2020).
colon cancer (1 paper, 2021). "The proteomic analysis of colon cancer indicated that the protein levels of TRAPPC3, TRAPPC4, TRAPPC5, and TRAPPC8 significantly correlated with that of PD-L116." (PMID 34518538, 2021).
cancer (1 paper, 2020). A tumor composed of atypical neoplastic, often pleomorphic cells that invade other tissues. "We investigated the localization of TRAPPC8 in ciliated cells and cancer cells with antibodies to TRAPPC8 and several intracellular organelle markers." (PMID 32258032, 2020).
infection (1 paper, 2013). The state of being infected such as from the introduction of a foreign agent such as serum, vaccine, antigenic substance or organism. "TRAPPC8 knockdown in HaCaT cells also showed reduced susceptibility to infection with authentic HPV31 virions, indicating that TRAPPC8 plays a crucial role in native HPV infection." (PMID 24244674, 2013). "In this study, using the two forms of HPV51 L2 as bait, we have performed a proteomic search for cellular proteins responsible for L2-dependent infection and report that the transport protein particle (TRAPP) complex subunit 8, TRAPPC8, coprecipitates with 51MaL2, but not with 51NuL2." (PMID 24244674, 2013).
TRAPPC8 also shares sentences with these, for which no sentence is quoted: spondyloepiphyseal dysplasia tarda (1 paper).